EGFR (epidermal growth factor receptor)
Diseases named in the same sentence as EGFR in open-access papers (continued):
Sharing a sentence is not in itself a finding about the gene and the disease.
ovarian carcinoma (continued). "Therefore, we speculate that the inhibitory effect of VM on ovarian cancer may be mediated through the EGFR/Ras/MEK/ERK signaling pathway." (PMID 38372808, 2024). "Inhibiting EGFR signaling could halt the malignant progression of ovarian cancer cells." (PMID 37964873, 2023). "Since activation of PI3K/p-Akt signal transduction is the main driver of cell growth, we hypothesized that SK may inhibit the transduction of EGFR/PI3K/AKT pathway through the estrogen signaling pathway, causing the inhibition of the growth of ovarian cancer cells." (PMID 36248433, 2022). "Since then, ST6Gal1-mediated activation of EGFR has been identified to influence survival, proliferation, apoptosis evasion, chemotherapy resistance, invasion and metastasis in a host of cancers including colorectal cancer ovarian cancer, and pancreatic ductal adenocarcinoma." (PMID 36106023, 2022). "Thus, we surmise that ovarian cancer cells might use STAT3 pathway activation to overcome EGFR inhibition, which leads to anti-EGFR antibody treatment failure." (PMID 34369236, 2021). "In addition, our data also indicated that miR-146b targets EGFR in ovarian cancer." (PMID 34369236, 2021). "EGFR might be an attractive therapeutic target since it is overexpressed in 70% of ovarian cancers." (PMID 34369236, 2021). "Therefore, it is reasonable to hypothesize that EGFR overexpression in artesunate-resistant ovarian cancer cells could impair the ability of artesunate to induce apoptosis through the BAD/Bcl-xL complex." (PMID 33652561, 2021). "Therefore, miR-146b might improve the antitumour activity of ovarian cancer therapy by blocking both the EGFR and STAT3 pathways." (PMID 34369236, 2021). "In this study, we found that EGFR could activate IL-6-STAT3 pathway in ovarian cancer cells." (PMID 34369236, 2021). "Interestingly, a recent study showed that treatment of ovarian cancer cells with neutralizing IL-6 antibodies resulted in upregulated EGFR, whereas the combination of neutralizing IL-6 antibodies and the EGFR inhibitor gefitinib exhibited enhanced anticancer activity." (PMID 35006432, 2021). "In addition to the effect of vitamin D on the proteins of the cell cycle signaling pathway, epidermal growth factor receptor (EGFR) has been identified in human ovarian cancer cell lines as a target gene leading to a sequential reaction which stops the cell cycle at the G1/S checkpoint." (PMID 32024052, 2020). "Moreover, manipulation of EGFR signaling by the use of an EGFR inhibitor AG1478 or LIMT through the overexpression system in ovarian cancer cells diminished cancer migration and metastasis that were mediated by TAMs in the co-culture system as well as in the xenografted mice." (PMID 32283687, 2020). "Hence, EGFR gene amplification in ctDNA might be a predictive marker for patients’ responsiveness to treatment in ovarian cancer." (PMID 33207545, 2020). "Furthermore, in anti-EGFR TKI-resistant ovarian cancer cells, anti-EGFR sensitization did not lead to de novo susceptibility to anti-EGFR agents." (PMID 31546690, 2019). "Based on our present results of increasing resistance of anti-EGFR-sensitive ovarian cancer cells to cetuximab by anti-EGFR TKI sensitization, we further examined whether sensitivity of ovarian cancer cells to death receptor ligands was impaired by anti-EGFR TKI sensitization." (PMID 31546690, 2019). "The EGF receptor (EGFR) (or HER) proto-oncogene family consists of four transmembrane tyrosine kinase receptors (i.e., EGFR, ErbB2, ErbB3, and ErbB4) that play a role in cancer pathogenesis and has been described as key therapeutic target in many types of cancer, including ovarian cancer." (PMID 32039018, 2019). "Intriguingly, in an in vivo ovarian cancer xenograft model, CAFs were found to efficiently promote the metastatic colonization of cancer cells in the intraperitoneal microenvironment, whereas the EGFR tyrosine-kinase inhibitor gefitinib inhibited the metastatic spread of ovarian cancer." (PMID 30568223, 2019).
ovarian carcinoma (continued). "Previous studies have demonstrated that the native ligand of epidermal growth factor receptor (EGFR) and ErbB4, heparin-binding EGF-like growth factor (HB-EGF), plays a critical role in the progression of ovarian cancer and is associated with prognosis of ovarian cancer." (PMID 30937184, 2019). "Since epidermal growth factor receptor (EGFR), which is highly expressed in ovarian cancer cells, is a very important factor for tumor growth, we therefore stimulated SKOV3 cells with EGF and performed MTT assay to evaluate whether KP still be able to suppress cell viability." (PMID 29891015, 2018). "Thus, EGFR may be a new therapeutic target for ovarian cancer, and may break through the bottleneck of current ovarian cancer treatment." (PMID 29482638, 2018). "In summary, our results suggest that co-expression of two, three or all four HER-family members and CD44 overexpression are common in patients with Stages III and IV ovarian cancers and that EGFR and CD44 expression at different cut off values may be of prognostic value." (PMID 29731973, 2018). "Moreover, cotreatment with an NRF2 inhibitor (bexarotene) can further repress the EGFR signalling pathway and might sensitize the ovarian cancer cells to the killing effects of lapatinib and/or erlotinib." (PMID 29410730, 2017). "While EGFR signaling is involved in promoting ovarian cancer cell proliferation, the results of the present study are in agreement with a number of previous analyses showing that EGFR tumor tissue staining by immunohistochemistry may be unpredictive of tumor progression." (PMID 28740577, 2017). "Despite a clear implication of EGFR, c-Src and Met in ovarian cancer progression and resistance to carboplatin, the inhibition of these proteins alone could be futile because of their capacity to stimulate the resistance between each other and the synergies they are able to establish." (PMID 28446239, 2017). "Moreover, previous study revealed that PAK4 could induce the expression of cyclinD1 through PAK4/c-Src/EGFR pathway in ovarian cancer cells." (PMID 27077843, 2016). "Therefore, high levels of TNF and frequent overexpression of EGFR observed in ovarian cancer could provide the fundamental basis for the higher expression of CCL20 in SKCXCR2-derived tumor tissues." (PMID 27723802, 2016). "Taken together, these results strongly suggest that EGFR may serve as one of the important cellular targets of monensin, and may explain in part the anti-proliferative activity monensin demonstrates against ovarian cancer cells." (PMID 26639992, 2015). "However, the role of EGFR and Her-2 in ovarian cancer aggregates is still poorly understood." (PMID 26617640, 2015). "Therefore, blocking the EGFR pathway could be an important strategy to improve the impact of targeted therapy in ovarian cancer." (PMID 25928246, 2015). "Intriguingly, our data point to dual mechanisms by which SPINK1 can promote ovarian cancer growth and progression: it appears to stimulate proliferation through an EGFR-dependent mechanism, while promoting resistance to anoikis through a serine protease-dependent, EGFR-independent mechanism." (PMID 26437224, 2015). "As we previously reported that inhibition of PAFR decrased ovarian cancer cell proliferation and the EGFR inhibition has shown promise in clinical trials in various types of cancers, including ovarian cancer, we asked whether simultaneously targeting the two receptors would have synergistic effects." (PMID 24886678, 2014). "However, the mechanisms underlying EGFR phosphorylation through PAF/PAFR in human ovarian cancer have not yet been tested." (PMID 25261977, 2014). "In this context, this study highlights the interest of the combination of an EGFR inhibitor with a BH3-mimetic molecule in two ovarian cancer cell lines (IGROV1-R10 and OVCAR-3) and suggests that this strategy might prove useful in improving the therapeutic care of ovarian carcinoma." (PMID 25299770, 2014).
ovarian carcinoma (continued). "However, the crosstalk between BRCA1 and EGFR signaling pathways in ovarian cancer remains largely unknown." (PMID 24321281, 2013). "Therefore, insights into the complex interrelationship between BRCA and EGFR might improve our understanding of the basic molecular mechanism of ovarian cancer." (PMID 24321281, 2013). "Therefore, it can be predicted that BRCA1 inactivation-related high levels of EGFR may be involved in promoting ovarian cancer progression." (PMID 24321281, 2013). "Clarifying the complex interactions between BRCA1 and EGFR signaling pathways at the transcriptional, posttranscriptional, and epigenetic levels may improve our understanding of the basic molecular mechanism of ovarian cancer." (PMID 24321281, 2013). "Therefore, EGFR is deemed to be a useful biomarker for ovarian cancers." (PMID 22481932, 2012). "The expression levels of GPR30, EGFR, ERα, and ERβ were analyzed using an immunohistochemical analysis, and their correlations with the clinicopathological features were examined in 10 patients with borderline malignant tumors and 152 patients with epithelial ovarian cancer." (PMID 23163984, 2012). "However, it is unclear whether GPR30-mediated Akt activation via EGFR transactivation occurs in ovarian cancer." (PMID 23163984, 2012). "Therefore, it was necessary to clarify whether GPR30 and the GPR30-dependent activation of MAPK-ERK1/2 via EGFR transactivation is important in ovarian cancer." (PMID 23163984, 2012). "Thus, a “cross-talk” between CXCL12/CXCR4 and EGFR intracellular pathways may link signals of cell migration and proliferation in ovarian cancer." (PMID 20049170, 2010). "Therefore, the inhibition of EGFR level by JMR-132 could be of significance in clinical treatment ovarian cancer." (PMID 20509930, 2010). "Hence, diminution in EGFR/IL-6R/STAT3 signalling may represent novel therapeutic targets for pharmacological intervention in the management of ovarian cancer progression." (PMID 19088723, 2009). "Our investigation revealed that TWP’s efficacy is driven by its ability to modulate five core targets—EGFR, JAK1, JAK2, PTPN11, and SRD5A1—which our analysis showed to be dysregulated in clinical ovarian cancer datasets." (PMID 41181611, 2025). "In the ovarian cancer cell line OVCAR8, we demonstrated that treatment with this antibody at 10 μg/mL for 24 h downregulated the levels of EGFR and FGFR4." (PMID 39858026, 2025). "Several tyrosine kinase inhibitors are under investigation and have been applied clinically in ovarian cancer, particularly those targeting vascular endothelial growth factor receptor (VEGFR) and epidermal growth factor receptor (EGFR)." (PMID 40395324, 2025). "Through integrated network analysis and clinical transcriptomic data, we identified five core targets (EGFR, JAK1, JAK2, PTPN11, and SRD5A1) that are differentially expressed in ovarian cancer tissues and serve as central nodes in TWP’s mechanism of action." (PMID 41181611, 2025). "Five cancer antigen-specific NIR-PIT agents targeting EGFR, Her2, FOLR1, TROP2, and TF were developed to selectively kill ovarian cancer cells." (PMID 41362788, 2025). "In epithelial ovarian cancer, ZKSCAN3 has shown a more complex oncogenic logic by forming a synergistic regulatory network with epidermal growth factor receptor (EGFR), which is a member of the receptor tyrosine kinase superfamily I." (PMID 40723888, 2025). "Our data also suggest that SORL1 interacts with EGFR and FGFR4, and their interactions are required to maintain the high levels of EGFR and FGFR4 proteins in ovarian cancer cells." (PMID 39858026, 2025). "The epidermal growth factor receptor (EGFR), which is overexpressed in up to 60% of ovarian cancers, upregulates expression of c-Myc and cyclin D1, promoting both aerobic glycolysis and cell cycle progression." (PMID 39639170, 2025).
ovarian carcinoma (continued). "Ovarian cancer cells pretreated with anti‐EGFR TKIs exhibit increased sensitivity toward NK cell‐mediated ADCC, suggesting EGFR‐TKI treatment can modulate the tumor cell surface properties, making them more susceptible to NK‐cell‐mediated killing." (PMID 40859900, 2025). "Separate investigations of EGFR inhibition in NSCLC and ovarian cancer models identified activation of STAT3 as being critical to the drug-tolerant state." (PMID 38473364, 2024). "It has been reported that the expression of HE4 in ovarian cancer is related to epidermal growth factor activity and pointed out that HE4 has a potential interaction with epidermal growth factor receptor (EGFR) or other cell surface receptors." (PMID 38742362, 2024). "CAR exosomes isolated from CAR-T cells loaded with cetuximab or trastuzumab scFv, respectively target and treat EGFR- or HER-2-positive breast and ovarian cancer." (PMID 38796525, 2024). "We used zebrafish xenograft models of ovarian cancer (OVCAR-5) and rhabdomyosarcoma (RD), together with EpCAM Chimeric Antigen Receptor (CAR-T) cells or epidermal growth factor receptor (EGFR)/CD3 bispecific T cell engagers (BiTEs), respectively." (PMID 38427724, 2024). "In both hepatocellular carcinoma and ovarian cancer, treatment with cisplatin leads to ADAM17-dependent release of cleaved growth factors and subsequent activation of the EGFR/PI3K/AKT pathway." (PMID 39506058, 2024). "Four transmembrane tyrosine kinase receptors from the EGF receptor (EGFR) or HER proto-oncogene family, which are involved in the etiology of many malignancies, such as ovarian cancer, are known to be significant therapeutic targets." (PMID 38496894, 2024). "AREG autocrine loops are activated in breast and ovarian cancer, and ectopic expression of AREG can induce an AREG/EGFR autocrine loop, rendering T cells EGF-independent." (PMID 38727313, 2024). "Resveratrol has also been found to inhibit ovarian cancer cell invasion, where lysophosphatidic acid (LPA) activates EGFR through Gi and G13, subsequently inducing Ras/Rho/ROCK signalling." (PMID 38673959, 2024). "In another study, it was found that aberrant activation of the EGFR/ERK signaling pathway can lead to the proliferation, survival, invasion, and drug resistance of ovarian cancer cells." (PMID 38372808, 2024). "The therapeutic potential of FLRT3 blockade to enhance T cell–based immunotherapies in solid tumors was tested in zebrafish xenograft models of ovarian cancer (OVCAR-5) and RD together with EpCAM CAR-T cells or EGFR/CD3 BiTEs, respectively." (PMID 38427724, 2024). "For example, in ovarian cancer cells, the interaction between EGFR and NTRK2 enhances the migration and proliferation of ovarian cancer cells by increasing the phosphorylation of AKT." (PMID 38791682, 2024). "Meanwhile, RUNX1 knockdown significantly decreased the phosphorylation level of EGFR and AKT in ovarian cancer cells." (PMID 38057816, 2023). "Interestingly, EGFR is over-expressed in up to 60% of ovarian epithelial malignancies, and its activation is associated with increased malignant tumor phenotype and poor patient prognosis, while VEGF indicated lower positive expression in ovarian cancer patients (25.0%)." (PMID 38057816, 2023). "Chemoresistant ovarian cancer cells exhibited increased GALNT14 expression, which led to enhanced tumor cell viability via the EGFR/mTOR signaling pathway." (PMID 37671061, 2023). "Although MICALL2 stabilized EGFR expression, it only stabilized the activation of its downstream AKT–mTOR signaling pathway in ovarian cancer cells." (PMID 38203692, 2023). "Under this premise, different types of LYTACs have proven efficient EGFR degradation in epithelial ovarian cancer and HCC cell lines using cetuximab, an EGFR-blocking antibody, as the POI ligand and conjugating it with M6Pn." (PMID 37896202, 2023).
ovarian carcinoma (continued). "Here, in ovarian cancer, our experiments strongly supported the notion that the oncogene EFEMP2 regulated the expression of PD-L1 driven by EGFR." (PMID 37420173, 2023). "Based on the phosphorylation pathway profiling array, EGFR and c-Jun were both lowly expressed after EFEMP2 was knocked down in ovarian cancer cells." (PMID 37420173, 2023). "MYC, EGFR, and CCND1 expressed at higher protein levels in ovarian cancer patients than in normal ovarian tissues." (PMID 35739532, 2022). "In this study, we demonstrated that SK promotes the apoptosis of ovarian cancer in vitro and in vivo, and its possible molecular mechanism by inhibiting the GPER-mediated EGFR/PI3K/AKT signaling pathway." (PMID 36248433, 2022). "In contrast to ATF3, the role of Amphiregulin (AREG), which is a low affinity ligand for epidermal growth factor receptor (EGFR), has been more established in ovarian cancer." (PMID 36131935, 2022). "Relying on the GESA analysis, we show that expression of geminin correlates with Aurora-A in mRNA and protein levels in human ovarian cancer, and the LPA signal stabilizes the geminin protein through the EGFR/Aurora-AThr288 axis." (PMID 36601056, 2022). "An increase in the expression level of mRNA and protein in women with ovarian cancer was observed for KRAS, c-FOS, PUMA, and EGFR." (PMID 35807169, 2022). "By decreasing EGFR phosphorylation and production of ERK and VEGF, PD inhibited the cellular aggregation of ovarian cancer cell lines in three dimensions." (PMID 36364001, 2022). "Correlation analysis was performed based on the expression of MYC, EGFR, and CCND1 in the TCGA-ovarian cancer dataset." (PMID 35739532, 2022). "The human ovarian cancer cell line, SKOV3, which expresses high levels of EGFR, HER2, and HER4, was used as a positive control for the expression of EGFR, HER2, and HER4." (PMID 36284301, 2022). "A study looking into a CP-specific prognostic biomarker for resistance in epithelial ovarian cancer suggested that MEK1, involved in the MAPK cascade and the greater EGFR pathway by enhancing proliferation and anti-apoptotic signals, is a strong candidate." (PMID 36499737, 2022). "It has been reported that miRNA-34c-5p represses amphiregulin-stimulated ovarian cancer drug resistance and stemness by downregulating the AREG/EGFR/ERK axis." (PMID 35342412, 2022). "For instance, Cetuximab, a chimeric monoclonal antibody that binds to the epidermal growth factor receptor (EGFR), was conjugated to cationic gold NPs to target ovarian cancer cells for the purpose of gene delivery." (PMID 35625966, 2022). "Previous studies confirmed that EGFR can enhance the expression of CXCR4 in some cancers, including breast and ovarian cancers." (PMID 35729596, 2022). "Lewis y significantly increased the proliferative capacity of ovarian cancer cells, which we subsequently found by activating PI3K/Akt signaling and promoting EGFR, TGF-β1, VEGF and b-FGF and other growth factors." (PMID 36544104, 2022). "At concentrations of 5–100 μM, PD was shown to suppress growth of the ovarian cancer cell lines SKOV-3 and OVCAR-8 by decreasing EGFR phosphorylation levels, which in turn increases the likelihood of the cells committing suicide." (PMID 36364001, 2022). "For example, anti-EGFR compounds and ALDH inhibitors in the NF-κB pathway have been utilized as therapeutic measures in ovarian cancer." (PMID 36531159, 2022). "Activated CXCR2 can also indirectly activate ERK MAPK via the transactivation of epidermal growth factor receptor (EGFR), in a mechanism identified in ovarian cancer cells." (PMID 35216283, 2022).